SOX1 (SRY-box transcription factor 1)
Diseases named in the same sentence as SOX1 in open-access papers (continued):
Sharing a sentence is not in itself a finding about the gene and the disease.
Lambert-Eaton myasthenic syndrome (12 papers, 2011 to 2026). Lambert-Eaton myasthenic syndrome (LEMS) is an autoimmune, presynaptic disorder of neuromuscular transmission characterized by fluctuating muscle weakness and autonomic dysfunction frequently associated with small-cell lung cancer (SCLC). "The presence of SOX1 antibodies in a patient with CD and Lambert-Eaton myasthenic syndrome points towards a wider association of different types of neuromuscular involvement." (PMID 40360002, 2025). "SOX1 antibody is an autoimmune antibody, usually associated with Lambert-Eaton myasthenic syndrome, paraneoplastic conditions, and encephalitis." (PMID 37946854, 2023). "The anti-SOX-1 antibodies have been mainly associated with Lambert-Eaton Myasthenic Syndrome (LETMS) and Small-Cell Lung Cancer (SCLC)." (PMID 36324062, 2022). "SOX1 antibodies are found in 64% of patients with Lambert-Eaton Myasthenic Syndrome(LEMS) in association with voltage-gated calcium channel antibodies as serological markers of SCLC." (PMID 34287773, 2022). "Anti-Sry-like high mobility group box (SOX1) autoantibodies have been described in various clinical conditions, including Lambert-Eaton myasthenic syndrome, paraneoplastic cerebellar degeneration and rare cases of paraneoplastic AIE." (PMID 40330578, 2025). "Anti-SOX1 antibodies have been linked to a number of clinical presentations, such as PCD and Lambert-Eaton myasthenic syndrome (LEMS)." (PMID 38322089, 2024). "Anti-SOX1 antibodies have been related to other neurological syndromes, including Lambert-Eaton myasthenic syndrome, polyneuropathy, and paraneoplastic cerebellar degeneration." (PMID 34056010, 2021). "All had lung cancer (small cell lung cancer [SCLC] in three), three with paraneoplastic cerebellar degeneration (PCD) and SOX1, CV2 (CRMP5) and Yo (PCA1) antibodies, and 1 with Lambert Eaton myasthenic syndrome and SOX1 antibodies." (PMID 32760403, 2020). "The frequency of SOX1 autoantibodies increases to 60% in patients with SCLC and paraneoplastic cerebellar degeneration (PCD) or Lambert-Eaton myasthenic syndrome (LEMS)." (PMID 31031763, 2019).
encephalitis (11 papers, 2020 to 2025). An acute inflammatory process affecting the brain parenchyma. "We report the first autopsy case of anti-SOX1 antibody-associated encephalitis accompanied by hippocampal sclerosis (HS)." (PMID 41394839, 2025). "This is the first documented case of HS proven by postmortem autopsy in a patient who succumbed to anti-SOX1 antibody-positive encephalitis associated with SCLC." (PMID 41394839, 2025). "Since SOX1 is an intracellular antigen, its associated encephalitis is expected to involve robust T-cell cytotoxicity." (PMID 41394839, 2025). "While chronic schizophrenia may contribute to baseline vulnerability or gliosis, the aggregate findings support the acute anti-SOX1 antibody–associated encephalitis as the driver of the severe HS observed at autopsy, rather than HS secondary to chronic structural pathology typically seen in mTLE." (PMID 41394839, 2025). "Twenty-eight were of anti-NMDA-receptor encephalitis with other cases associated with antibodies against LGi1, Caspr2, glycine receptor, DPPX, GABAB receptor, IgLON5, GFAP, and SOX1." (PMID 33692738, 2021). "Eleven cases were diagnosed with anti-NMDA receptor encephalitis, 4 cases with anti-Ma2 encephalitis, 3 cases with anti-GAD encephalitis, and 1 case with anti-SOX1 encephalitis." (PMID 34056010, 2021). "Anti-SOX1 encephalitis is an exceptional condition in pediatric population." (PMID 34056010, 2021). "In the anti-SOX1 encephalitis cases, 50% experienced flu-like illness and fever." (PMID 33692738, 2021). "In our series, we reported an exceptional case of anti-SOX1 encephalitis in a 12-year-old girl." (PMID 34056010, 2021). "In patients with encephalitis and HuD antibodies as well as serum and CSF SOX1 antibodies were reported in a 59-year-old female suffering from cognitive impairment, recalling that the contribution of SOX1 antibodies to cognitive impairment remains unknown." (PMID 33026492, 2021). "Movement disorders were objectified in 8 cases with anti-NMADR encephalitis, 1 case with anti-GAD65 encephalitis, and 1 case with anti-SOX1 encephalitis." (PMID 34056010, 2021). "Similarly, the most commonly reported autoantibodies associated with GABABR autoimmune disease were anti-Hu (10.8%), anti-SOX1 (10.8%) and anti-GAD65 (8.5%), as summarized by a review of 94 cases with anti-GABABR encephalitis." (PMID 35515002, 2022).
nasopharyngeal carcinoma (11 papers, 2010 to 2026). A carcinoma arising from the nasopharyngeal epithelium. "It has been reported that SOX1 can inhibit cervical, liver, and nasopharyngeal carcinomas through the Wnt/β-catenin signaling pathway." (PMID 32675943, 2020). "SOX1 has been demonstrated to down‐regulate β‐catenin and reverse the malignant phenotype in nasopharyngeal carcinoma." (PMID 32918341, 2020). "In this study, we show that SOX1 induces nasopharyngeal carcinoma (NPC) cells to enter a quiescent state." (PMID 37369660, 2023). "Albeit a number of these proteins have been shown to play a role in cancer, we chose to investigate the role of Sox1 in our model since it is very homologous to the induced pluripotent stem cell (iPS) regulator Sox2, and has been shown to play a role in progression of lung and nasopharyngeal cancer." (PMID 20929579, 2010). "It is well known that SOX1 represses β-catenin-mediated TCF/LEF signaling by interaction with β-catenin in hepatocellular carcinoma and nasopharyngeal carcinoma (NPC)." (PMID 37190139, 2023).
hepatocellular carcinoma (10 papers, 2015 to 2025). A malignant tumor that arises from hepatocytes. "For example, SOX1 was reported to inhibit hepatocellular carcinoma progression by mediating Wnt/β-catenin pathway." (PMID 35611828, 2022). "Indeed, epigenetic silencing of SOX1 was reported in hepatocellular carcinomas." (PMID 39272828, 2024). "NR2F1-AS1 targets SOX1 via sponging miR-363 to regulate the progression of endometrial cancer and induces oxaliplatin resistance through miR-363 to target ABCC1 in hepatocellular carcinoma." (PMID 34408977, 2021). "High SOX1 expression has been identified as a negative prognostic biomarker in cancer, with reduced SOX1 protein and/or mRNA levels correlating with poorer prognosis and shorter overall survival in ovarian cancer, hepatocellular carcinoma, and oesophageal squamous cell carcinoma." (PMID 40159622, 2025).
lung carcinoma (10 papers, 2010 to 2025). "The findings of this study confirm the robust association between the occurrence of SOX1 autoantibodies and the presence of lung cancer and show the limitations of the immunohistochemical and line blot assays in the detection of these antibodies." (PMID 31031763, 2019). "All 17 (100%) patients with SOX1-abs detected by CBA had lung cancer, that was SCLC in 16 (94%), and a definite diagnosis of PNS was established in 15 (88%)." (PMID 37207233, 2023). "Knockdown of SOX1 expression by doxycycline withdrawal significantly reversed colony formation and cell invasion of lung cancer cells." (PMID 37190139, 2023). "Then, we analyzed the methylation level and mRNA expression of SOX1 in lung cancer cell lines using quantitative MSP (qMSP) and quantitative RT-PCR (qRT–PCR)." (PMID 37190139, 2023). "We used quantitative methylation-specific polymerase chain reaction (MSP), quantitative reverse transcription polymerase chain reaction (RT–PCR) analysis, and web tools to confirm the frequent epigenetic silencing of SOX1 in lung cancer." (PMID 37190139, 2023). "Phenotypic rescue experiments further suggested that downregulation of HES1 contributes to the suppressive effect of SOX1 on colony formation and cell invasion in lung cancer." (PMID 37190139, 2023). "Collectively, these data suggest that the downregulation of HES1 contributes to the suppressive effect of SOX1 in lung cancer." (PMID 37190139, 2023). "Overexpression of SOX1 in an inducible system significantly suppressed the malignant phenotype of a lung cancer cell line, whereas knockdown of SOX1 expression partially restored cancer cell invasion and anchorage-independent growth." (PMID 37190139, 2023). "The main finding of this study is that all samples with SOX1-abs determined with the commercial line blot and confirmed by TBA were also positive by CBA and associated with lung cancer (100%) and definite diagnosis of PNS (88%)." (PMID 37207233, 2023). "We proved that SOX1 methylation inversely correlated with its mRNA expression levels in lung cancer cell lines." (PMID 37190139, 2023). "The neurological diagnosis of the remaining four patients, two had myasthenia, thymoma, and CV2 (CRMP5) antibodies, and two had brain metastasis in the setting of lung cancer and SOX1 and Ma2 antibodies." (PMID 32760403, 2020). "To further investigate whether SOX1 could inhibit the Wnt signaling pathway in lung cancer, we applied a Wnt/TCF-responsive luciferase reporter assay." (PMID 37190139, 2023). "Interestingly, downregulation of HES1 contributes to the suppressive effect of SOX1 on colony formation and cell invasion in lung cancer." (PMID 37190139, 2023). "The expression and function of SOX1 in the progression of lung cancer are still unclear." (PMID 37190139, 2023). "However, the role of SOX1 in the development of lung cancer is unclear." (PMID 37190139, 2023). "The expression and function of SOX1 in the development of lung cancer remain unclear." (PMID 37190139, 2023). "SOX1-abs were confirmed by CBA in 17 (50%) patients, all (100%) had lung cancer (SCLC in 16) and 15/17 (88%) had a PNS." (PMID 37207233, 2023). "Restoration of SOX1 expression repressed HES1 via the direct binding of SOX1 to the HES1 promoter region and inhibited the malignant phenotype of lung cancer cells." (PMID 37190139, 2023). "In this study, we demonstrated that the SOX1/HES1 axis contributes to cancer growth and invasion in lung cancer." (PMID 37190139, 2023). "Indeed, overexpression of SOX1 significantly repressed the expression of HES1 at both the mRNA and protein levels in two lung cancer cell lines." (PMID 37190139, 2023). "An important observation of our study is that 50% of patients positive for SOX1-abs by line blot were negative by CBA and, unlike those that were CBA positive, they had a wide array of neurological diagnoses without lung cancer association." (PMID 37207233, 2023).
lung carcinoma (continued). "If we exclude the 30 patients with SOX1 autoantibodies that were selected from our database of PNS, the clinical data of the remaining 41 patients whose samples were sent for onconeuronal antibody testing confirmed the specificity of SOX1 autoantibodies for PNS and lung cancer." (PMID 31031763, 2019). "The remaining 15 (44%) samples were TBA negative, 13 of them also negative by CBA; the 2 (13%) cases positive by CBA but negative by TBA were from patients with PNS and lung cancer, supporting our previous observation that a small subset of SOX1-abs positive samples are not detected by TBA." (PMID 37207233, 2023). "However, no antibodies typically found in patients with lung cancer and PND, including anti-Hu, anti-CV2/CMRP5, anti-amphiphysin, anti-VGCC, anti-SOX1, anti-GABABR and anti-AMPAR, were present in our patients." (PMID 27776522, 2016).
ovarian carcinoma (9 papers, 2013 to 2025). A malignant neoplasm originating from the surface ovarian epithelium. "Methylated HIC1 and SOX1 exhibited a similar trend to identify ovarian cancer at various stages of disease (70.0% (14/20) of stage I/II, 85.2% (46/54) and 83.3% (45/54) of stage III, respectively, and 72.7% (8/11) of stage IV ovarian cancers)." (PMID 34778370, 2021). "Hypermethylated SOX1 was also found in ovarian cancer cells that are chronically exposed to cisplatin." (PMID 27738327, 2016). "The methylation of SOX1 has been reported as being correlated with the recurrence of ovarian cancer and with overall survival rates for patients with ovarian cancer." (PMID 24565108, 2013). "The combined panel of HOXA9 + HIC1 and HIC1 + SOX1 exhibited the best discriminatory efficiencies at all stages of ovarian cancer (100.0% (10/10) of stage I/II, 80.0% (24/30) and 70.0% (21/30) of stage III, respectively and 80.0% (4/5) and 100.0% (5/5) of stage IV of ovarian cancer, respectively)." (PMID 34778370, 2021). "Simultaneous methylation of SOX1+HOXA9 exhibited positivity for methylation in 75.0% (15/20) of stage I/II, 85.2% (46/54) of stage III, and 81.8% (9/11) of stage IV of ovarian cancer." (PMID 34778370, 2021). "Herein, the promoter methylation of seven ovarian cancer-specific genes (RASSF1A, DAPK1, SOX1, HOXA9, HIC1, SPARC, and SFRP1) was analyzed quantitatively in 120 tissue samples by MethyLight assay." (PMID 34778370, 2021). "Methylation pattern was analyzed in ovarian cancer tissue samples through clonal sodium bisulfite DNA sequencing in the promoter region harboring a total of 19, 14, and 26 CpG sites for HOXA9, HIC1, and SOX1 gene, respectively." (PMID 34778370, 2021). "Moreover, higher sensitivity in identifying early stages of ovarian cancer was exhibited by HOXA9, HIC1, and SOX1, which further confirms their utility as a potential biomarker for early-stage detection of EOC." (PMID 34778370, 2021). "Similarly, the two-gene panel of SOX1 + HOXA9 was found positive for methylation in 80.0% (8/10) of stage I/II, 56.7% (17/30) of stage III, and 80.0% (4/5) of stage IV ovarian cancers." (PMID 34778370, 2021). "In addition, our findings showed that the methylation levels of candidate genes (HIC1, HOXA9, SOX1, DAPK1, RASSF1A, SFRP1, and SPARC) were significantly elevated in patients with ovarian cancer and was highly cancer-specific, which is in concord with the previously published reports." (PMID 34778370, 2021). "Methylated HOXA9, HIC1, and SOX1 exhibited a similar trend to identify ovarian cancer at various stages of disease in 70.0% (7/10) patients with stage I/II cancer, 56.7% (17/30), 70.0% (21/30), and 43.3% (13/30) of stage III, respectively and 80.0% (4/5) of stage IV ovarian cancer patients." (PMID 34778370, 2021).
paraneoplastic neurological syndromes (9 papers, 2019 to 2026). "SOX1 antibodies (SOX1-abs) are associated with paraneoplastic neurological syndromes (PNS) and small cell lung cancer (SCLC)." (PMID 37207233, 2023). "SOX1 antibodies (SOX1-abs) are serological markers of paraneoplastic neurological syndromes (PNS) associated with small cell lung cancer (SCLC)." (PMID 37207233, 2023). "Anti-titin and anti-SOX1 often present with other classical paraneoplastic antibodies (anti-Hu, Ri, Yo etc.)in paraneoplastic syndrome of the nervous system." (PMID 31694559, 2019). "The exact mechanisms by which anti-SOX1 antibodies exert their effects are not completely understood; however, they are thought to be associated with cancers, especially small-cell lung cancer (SCLC), which is the tumor type most often found in patients with paraneoplastic neurological syndromes." (PMID 41394839, 2025). "However, anti-SOX1-ab are not specific to LEMS, and may be found in other paraneoplastic neurological syndromes, or in SCLC alone; anti-SOX1-ab are therefore a marker of paraneoplastic neurological syndromes." (PMID 39555481, 2024).
breast carcinoma (8 papers, 2010 to 2023). "Although SOX1 has yet to be implicated as a regulator of aggression in prostate cancer, it has been implicated as a marker of CSCs in breast cancer." (PMID 20929579, 2010). "Using either CD44+/CD24- or CD133+ cells isolated from Brca1-deficient mouse mammary tumors, expression of Sox1 was found to be significantly higher in these cells when compared to their counterparts." (PMID 20929579, 2010). "In breast cancer, SOX1 is activated due to the loss of miR-335, which was also found down-regulated in our study suggesting that miR-129 might also play a role in the SOX1 mediated acquisition of metastatic capacity." (PMID 22438871, 2012). "Both populations were highly tumorigenic – as few as 50 to 100 CD44+/CD24− and CD133+ breast cancer cells induced tumors in NOD/SCID mice – and expressed stem cell associated genes, including Oct4, Notch1, Aldh1, Fgfr1 and Sox1." (PMID 32430004, 2020).
bladder cancer (5 papers, 2018 to 2025). "Another study reported that SOX1 gene methylation is associated with the prognosis prediction of bladder cancer." (PMID 32849763, 2020). "Genome-wide methylation analysis of bladder cancer tissues discovered hypermethylation in the promoter region of a number of genes; with the combined hypermethylation of SOX1, PITX2, or versican identifying patients with a higher risk of bladder cancer morbidity." (PMID 29559954, 2018). "For bladder cancer, a perfect score (100%) was found for both sensitivity and specificity in the SOX1, TJP2, MYOD, HOXA9_1, and HOXA9_2 panel." (PMID 40141826, 2025). "Biomarkers with high sensitivity and specificity in multiple panels include RUNX3, SOX1, IRF8, and DAPK; these were used specifically for diagnosis of bladder cancer." (PMID 40141826, 2025). "SOX-1, IRAK3, and Li-MET are characterized by detecting changes in DNA methylation within bladder cancer cells shed in urine, achieving sensitivity of 86% and specificity of 89%." (PMID 37762677, 2023). "Additionally, the promoter-hypermethylations of LMX1A, SOX1, and ZNF177 were previously reported in lung, stomach, and bladder cancers, respectively, by other groups." (PMID 31547144, 2019).
cerebellar ataxia (5 papers, 2013 to 2025). A neurological syndrome characterized by clumsy and uncoordinated movement of the limbs, trunk, and cranial muscles. "The practical implication of our study is that in patients with cerebellar ataxia, SOX1-ab are good predictors of an associated SCLC with a specificity of 100% and a sensitivity of 49%." (PMID 23536908, 2013). "Our data indicate that SOX1-ab are good predictors of an underlying SCLC in patients with cerebellar ataxia." (PMID 23536908, 2013). "Anti-SOX-1 antibodies cross-react with the nuclei of cerebellar Bergmann glial cells and induce cerebellar ataxia." (PMID 39860369, 2025). "SOX1-ab are predictors of SCLC in ataxia patients with a specificity of 100% and sensitivity of 49%." (PMID 23536908, 2013). "His cerebellar ataxia may be attributable to the combined effects of all three detected antibodies-anti-CV2/CRMP5, anti-Hu, and anti-SOX1." (PMID 41542009, 2025). "First, no banked serum prevented cell-based assays (CBA) for neuronal surface antibodies (e.g., anti-GABABR, anti-AMPAR1/2) and anti-SOX1 serology; P/Q-type VGCC testing to exclude subclinical LEMS/ataxia was not possible." (PMID 41394839, 2025).
gastric cancer (5 papers, 2016 to 2023). A primary or metastatic malignant neoplasm involving the stomach. "Transwell assay and Scratch-healing migration assay was used to investigate the role of MRTF-A and SOX1 in gastric cancer cell migration and invasion." (PMID 32675943, 2020). "MRTF-A inhibited the inhibitory effects of SOX1 on gastric cancer cell migration by promoting the express -ion of miR-155." (PMID 32675943, 2020). "miR-155 promotes gastric cancer cell migration by suppressing SOX1 expressiom by targeting its 3′UTR in vitro and in vivo." (PMID 32675943, 2020). "The results showed that overexpression of SOX1 significantly suppressed the migration and invasion of gastric cancer cells." (PMID 32675943, 2020). "We next sought to determine whether MRTF-A regulated the SOX1 gene through miR-155 in gastric cancer cells." (PMID 32675943, 2020). "We next examined whether MRTF-A regulated the SOX1 gene through miR-155 in gastric cancer cells, MRTF-A inhibition significantly suppressed the expression of SOX1." (PMID 32675943, 2020). "Integration analysis of SNPs and gene expression profile revealed that FOXL1 regulated the most important DEGs of IRX1, SOX1, and MSX1 with risk associated SNP loci, which may serve as candidate biomarkers for diagnosis and prognosis of gastric cancer." (PMID 27403158, 2016).